PML (PML nuclear body scaffold)
Diseases named in the same sentence as PML in open-access papers (continued):
Sharing a sentence is not in itself a finding about the gene and the disease.
tumor (continued). "PML is located in chromosome 15q24, and PML together with its interacted partners formed one sub-nuclear structure through multimerization and organization, which is also known as NBs, to perform its function of tumor suppression and genomic stability maintenance." (PMID 33957999, 2021). "However, the effects of PML perturbation on the bulk of tumor cells remained poorly understood." (PMID 31570853, 2020). "Hence, since its discovery PML is implicated in playing a role in carcinogenesis and more often than not vouched as a tumor suppressor." (PMID 31506431, 2019). "Thus ERβ induction is important for enhanced expression of PML, leading to activation of tumor suppressors Foxo3a, p21 and caspases, reduction of pro-oncogenic molecule Survivin, and subsequent effect on apoptosis and tumor suppression." (PMID 31506431, 2019). "However, when liver tissue of PML−/−HCVtg mice that did develop liver tumors was assessed, there was a significant increase of Ki67‐positive nuclei of up to 14% in the tumor‐surrounding tissue (TST) and up to 60% in the tumor tissue (TT) itself when compared to all other experimental groups." (PMID 31144474, 2019). "Nuclear domain 10 (ND10), also called PML nuclear bodies (PML-NB), are discrete nuclear structures involved in a multitude of pathways including protein degradation, transcriptional regulation, cellular senescence, tumor suppression, DNA repair, apoptosis and epigenetic regulation." (PMID 25033267, 2014). "As the overexpression of RNF4 alone is sufficient to induce a proteasome-dependent PML degradation, it will be interesting to assess whether RNF4 expression is increased in cancer and whether this can be correlated with a decrease of PML expression and tumor aggressiveness." (PMID 23734343, 2013). "PML, in addition to its own anti-tumor activity, contributes to the assembly of an integrated and superior network that may be necessary for the maximization of the tumor suppressor response to diverse oncogenic insults." (PMID 23459691, 2013). "Moreover, the few PML mutations detected did not correlate with PML protein-loss, suggesting that mutation is not the main mechanism of PML inactivation in the tumor types analyzed." (PMID 23847764, 2013). "Interestingly PML mutants resistant to CK2-phosphorylation increase tumor suppressive functions." (PMID 23734343, 2013). "Thus, PML functions cannot be considered univocally tumor suppressive." (PMID 23847764, 2013). "PML bodies also seem to play a multifaceted role in various cellular processes, including cell proliferation, cellular senescence, apoptosis, and tumor suppression so that the function of PML bodies may well be an important contributing factor in the pathogenesis of malignant tumors." (PMID 19025608, 2008). "The inhibition of PML expression leads to reduced levels of MYC and PIM1 kinases, while promoting the accumulation of CDKN1B, which results in a stagnation of tumour cell growth and triggers cellular senescence." (PMID 40211955, 2025). "To investigate the therapeutic potential of As2O3 on ALT inhibition, we examined the ability of As2O3 to target PML bodies and APB formation in tumor xenografts generated by subcutaneously injecting SaOS2 ALT cancer cells into nude mice." (PMID 38752489, 2024). "In conclusion, a comprehensive analysis of shelterin components in ALT cells is needed to further understand the role of shelterin in telomere HR and recruitment to PML bodies and to expand new targets for the treatment of ALT tumor cells." (PMID 38069153, 2023). "Promyelocytic leukemia protein (PML) can increase lipid peroxidation, regulate mitochondrial metabolism and iron metabolism in tumor cells, and then enhance the chemosensitivity of HGSC." (PMID 36090052, 2022). "The principal organizing component of PML bodies is the PML protein, a member of the TRIM/RBCC family protein and a type of tumor suppressor gene." (PMID 35805146, 2022).
tumor (continued). "Tumor suppressors such as PTEN, BAP1, and PML have been shown to induce apoptosis in cancer cell by promoting IP3R3-mediated Ca2+ flux from the ER to mitochondria." (PMID 34518526, 2021). "Among these ten genes, the expression levels of SETD1B, ACSF2, MUC1, KLHL24, PML, MT1G, and GPT2 were higher in tumor tissues than those in normal tissues, while HIC1, AKR1C1, and LOC390705 were lower expressed in tumor tissues." (PMID 35071242, 2021). "This condition is an essential part of the tumor-promoting effect of TRAIL-R2 in particular when localized in the nucleus and impacting on PML-nuclear domains." (PMID 34333527, 2021). "Here, we reached similar conclusions and also detected co-localization events between telomeres and PML in healthy human lung tissue, thus reducing the confidence in the APB assay to identify the ALT phenotype on tumor sections." (PMID 35006465, 2021). "This review discusses and highlights some of these exceptions; the genetic events, cellular contexts, and mechanisms by which four important tumor suppressors—pRb, PTEN, FOXO, and PML display their oncogenic potentials and pro-survival traits in cancer." (PMID 33396222, 2020). "The tumor spheres derived from the OTUD5-depleted cells and PML-depleted cells grew faster and had greater weight than those excised from the control cells, while TRIM25 knockdown inhibited tumor sphere formation." (PMID 32826889, 2020). "In this study, we demonstrate that PML depletion in the bulk of TNBC cells in culture and in vivo triggers a tumor suppressive response consisting on growth arrest and the activation of senescence." (PMID 31570853, 2020). "This chemotherapy increases the level of PML in MAMs and increases IP3R-mediated calcium transfer between the ER and mitochondria, thereby promoting the apoptosis of tumor cells and reducing autophagy." (PMID 30931098, 2019). "Interestingly, PML loss causes in prostate tumors a MAPK activation that in turn elicited the activation of a sterol regulatory element-binding protein (SREBP) prometastatic lipogenic program; in vivo targeting of SREBP using a fatostatin blocked tumor growth and metastatic activity." (PMID 31366128, 2019). "PMLis a well-established tumour suppressor and a reduction orloss in expression of PML in other systems, e.g. in PML−/−mice, results in increased proliferation and reduced apoptosis." (PMID 28754805, 2017). "It is worth mentioning the direct phosphorylation of PML by CK2 at Ser517, which promotes the proteasome-dependent degradation of PML, thus preventing its tumour-suppressive activity." (PMID 28031292, 2017). "Consistent with these tumor-promoting functions, aberrant expression of several key molecules of the KLHL20/PML pathway, such as HIF-1α, Pin1, and PML, has been reported in many types of cancers." (PMID 27042198, 2016). "Representative FISH images of PML (red) and RARA (green, used as control) genes in primary tumor (P1-P6) and recurrence (IR1-IR2 and ER1-ER4) samples." (PMID 26620706, 2015). "It would be interesting to characterize which PML isoform regulates FAO and performs an unexpected tumor oncogenic role." (PMID 23761861, 2013). "PML-RARα binds and recruits Mi-2/NuRD-HDAC to the tumour-suppressor gene RARβ2 to silence the RARβ2 promoter." (PMID 23658227, 2013). "Multivariable analysis indicated that the number of PML-NBs is the most significant independent factor correlating with HLA class I expression in EBV+ cHL, while the percentage of SATB1+ tumor cells also had an independent effect." (PMID 24009715, 2013).
tumor (continued). "Taken together, it makes sense that tumor cells would not select for the genomic loss of PML, as is seen with some classical tumor suppressor genes, since it would be irreversible and would prevent cells from utilizing the PML-mediated pro-survival or pro-self renewal pathways when challenged." (PMID 23936764, 2013). "We analyzed HLA class I, number of PML nuclear bodies (NBs) and SATB1 expression in tumor cells of 54 EBV+ cHL cases and used 27 EBV− cHL cases as controls." (PMID 24009715, 2013). "The cPML-RARα disrupts cPML-Smad2/3 interaction and antagonizes the tumor suppressive TGF-β signaling, providing an additional mechanism for PML-RARα oncogenic function." (PMID 23761861, 2013). "Our work has revealed a direct crosstalk between PML and YAP, one of the two main effectors of the Hpo tumor suppressor pathway." (PMID 23459691, 2013). "Multivariable analysis indicated that the number of PML-NBs and the percentage of SATB1+ tumor cells are independent factors affecting HLA class I expression in EBV+ cHL." (PMID 24009715, 2013). "Moreover, TRIM19/PML may act as a tumour suppressor protein." (PMID 22649727, 2012). "Intriguingly, we found that PML is required for normal expression of class I MHC HLAs, thereby suggesting a potential novel mechanism by which PML functions as a tumor suppressor." (PMID 22947142, 2012). "Moreover, in human non-small cell lungcancers, there is an inverse relationship between PML expression and CK2 activity.Since PML is a nuclear-matrix-associated protein, a nuclear accumulation of CK2 maybe functionally relevant to inactivate the tumor-suppressive functions of PML." (PMID 21359197, 2011). "However, elevated PML expression can lead to resistance to ATO by upregulating ALDH3A1, which diminishes the anti‐tumour effect of ATO." (PMID 40211955, 2025). "In addition, nuclear p62 condensates interact with and stabilize PML-NBs, an established tumor suppressor, by sequestering and promoting degradation of RNF4, its Ub E3 ligase, which otherwise would have targeted PML for proteolysis." (PMID 41247240, 2025). "While accurately discerning differences in gene expression between liver normal and tumor tissues might be challenging, preliminary findings revealed elevated expressions of G6PD, STMN1, and PML in HCC tissues in comparison to normal liver tissues." (PMID 38317842, 2024). "The identified CK2-SALL2 axis may be part of a broader mechanism where CK2 downregulates the stability of multiple tumor suppressors in the cell, including iκB, VHL, PML, and SALL2, by phosphorylating residues near or within PEST motifs." (PMID 38493149, 2024). "However, the staining intensity of the signature proteins—PML, G6PD, SLC7A11, and STMN1—in the tumor tissues was notably stronger than that in the paired adjacent tissues." (PMID 38317842, 2024). "PML protein was initially identified as a fusion partner of RARα in APL and is a tumor suppressor." (PMID 39253293, 2024). "Taken together, these results demonstrate that ccRCC cells are addicted to PML expression, thus suggesting a novel non-oncogenic dependency in this tumor type." (PMID 38730056, 2024). "In line with this hypothesis, we observed UBC9 mRNA and protein overexpression in ccRCC tumor samples, and positive correlation of UBC9 and PML mRNA expression." (PMID 38730056, 2024). "Mass spectrometry pan-cancer proteomic data provided by the NCI Clinical Proteomic Tumor Analysis Consortium (CPTAC) confirmed that the PML protein is markedly overexpressed in ccRCC (kidney renal clear-cell carcinoma; KIRC) compared to paired normal adjacent tissue." (PMID 38730056, 2024). "For example, the lack of PML in combination with HCV is associated with increased cell proliferation, fostering tumor development in the liver." (PMID 39062197, 2024).
tumor (continued). "This is particularly evident in cancer, where PML is at large nongenetically deregulated and exerts oncogenic or tumor-suppressive functions depending on the tumor context." (PMID 38730056, 2024). "PML‐KD did not affect significantly the local tumor growth or the non/low metastatic properties of MCF7 cells." (PMID 37518985, 2023). "The leukemic cells of the other six PML::RARA-negative AML cases with APL-like morphological features, except the KMT2A-positive patient (due to the specific tumor biology), had more or less a typical myeloid immunophenotype, with strong expression of pan-myeloid antigens (CD33, CD13, MPO)." (PMID 36980947, 2023). "ATO reportedly destroys CML cells by reducing PML expression and kills CML tumor stem cells." (PMID 35707364, 2022). "A single cell-based mathematical model was developed to describe the evolution of tumor spheroids in different conditions and discriminate the differential behavior between non-induced and PML OE-U87MG cells." (PMID 34208139, 2021). "The TF–target gene network analysis uncovered an unexpected scenario where both correlation-enhancing genes (with higher correlation in the tumor) and -repressing genes (with lower correlation in the tumor) were targeted by STAT1 (6A), STAT3 (6B), KDM1A (6C), PML and RELA." (PMID 33384992, 2020). "PML staining was detected in both the cytoplasm and nucleus of the epithelial cells from tumor and nontumor tissues (right)." (PMID 32826889, 2020). "The PML expression was markedly downregulated in the tumor tissues than it was in the adjacent noncancer tissues (right and 8d, right)." (PMID 32826889, 2020). "The Promyelocytic Leukemia protein (PML), the essential component of the PML nuclear bodies (PML-NBs), induces apoptosis and inhibits angiogenesis and cell cycle progression in cancer, thus complying with the definition of a tumor suppressor." (PMID 31570853, 2020). "Within the PML−/−HCVtg group, 40% of all animals presented with at least one macroscopic tumor by the age of 12 months, whereas there were no lesions present in livers of mice of the three other groups (HCVtg, PML or WT)." (PMID 31144474, 2019). "The lack of PML in combination with HCV is associated with increased cell proliferation, fostering tumor development in the liver." (PMID 31144474, 2019). "Our data suggest that within PML‐deficient and HCV‐transgenic mice, NLRP12 is downregulated in tumor tissue on an RNA level, but not on a posttranscriptional level." (PMID 31144474, 2019). "Taken together, loss of expression in many (but not all) cancer types have suggested that PML works as a tumor suppressor." (PMID 29888200, 2018). "Furthermore, KLHL20 is upregulated in certain tumors and possesses pleiotropic tumor-promoting functions through potentiating the degradation of tumor suppressor proteins DAPK and PML." (PMID 27042198, 2016). "Interestingly, PML is also reported to contribute to GBM resistance to mTOR targeted therapies, suggesting its involvement in GBM tumor progression." (PMID 26510911, 2015). "No change in PML expression was observed in A/E9a;Nras tumor cells treated in vitro for 24 hours with either vehicle (DMSO) or panobinostat." (PMID 25628765, 2015). "Marked by PML and SP100, PML-NBs are subnuclear compartments in eukaryotic cells enriched in regulatory proteins that can modulate multiple cellular processes including gene transcription, tumor suppression, as well as DNA replication and repair." (PMID 24563217, 2014).
tumor (continued). "Open questions remain, however, regarding PML and its functions, that will no doubt motivate further investigation of this intriguing tumor suppressor." (PMID 23504288, 2013). "Altogether, the emerging picture is that of a context-dependent contribution of PML to both tumorigenesis and tumor suppression, and it is not possible to conclude which way the balance tilts." (PMID 23847764, 2013). "There was a significant correlation between PML protein and mRNA expression only in tumor (not stroma) cells." (PMID 23936764, 2013). "While the nuclear promyelocytic leukemia (PML) protein functions as a tumor suppressor, cytosolic PML was reported to specifically inhibit tetrameric but not dimeric PKM2 activity, thereby contributing to the Warburg effect." (PMID 23476652, 2013). "For example, a particular class of PML-NBs exists in tumor cells that maintain their telomeres without telomerase activity by a process referred to as alternative lengthening of telomeres (ALT)." (PMID 23990779, 2013). "Because PML is down-regulated in many cancers, we suspect the down-regulation of PML and thereby class I MHC HLAs is one of the mechanisms used by cancers to escape the anti-tumor immune response." (PMID 22947142, 2012). "Promyelocytic leukemia protein (PML) is a tumor suppressor that is highly expressed in endothelial cells nonetheless its role in endothelial cell biology remains elusive." (PMID 22947142, 2012). "Therefore, we propose that PIN1 may function as a key mediator of PML-NB during OIS and is necessary for the upregulation of tumor suppressor genes in response to RasG12V activation." (PMID 38216124, 2024). "Of note, previous studies identified that Wdr4 exerts multiple functions, such as regulating tumor microenvironments, stabilizing tRNA, and maintaining genome stability, through interacting with different partners/effectors, including DDB1/PML, METTL1, and FEN1, individually." (PMID 36681682, 2023). "Therefore, our findings suggest that a subset of TNBC patients with more TLS or lower expression of PML and PLOD3 in tumor will be the group who may benefit more from camrelizumab combined with apatinib and eribulin." (PMID 35641481, 2022). "Moreover, we demonstrate that OTUD5 plays a previously unknown role in transcriptional regulation and tumor suppression by deubiquitinating TRIM25, leading to the downregulation of PML and fewer PML-NBs." (PMID 32826889, 2020). "Similarly, promyelocytic leukemia protein (PML), which is a tumor suppressor, is located at the MAMs and controls the formation of autophagosomes by regulating the activity of the AMPK/mTOR/ULK1 pathway via affecting the transport of calcium ions from the ER to mitochondria." (PMID 32766245, 2020). "This phenomenon might have been overlooked in prior studies due to the lack of data at the time on the role of PML favoring cancer cell function in specific tumor subsets." (PMID 31570853, 2020). "No tumor development was observed in mice with either the PML‐knockout (PML−/−) or HCVtg alone." (PMID 31144474, 2019). "However, the precise role of the APL-associated PML-RARα oncoprotein and PML-NB integrity in the DSB response in APL leukemogenesis and tumor suppression is still lacking." (PMID 27468685, 2016). "Consistent with these tumor suppressive functions, the expression of PML protein, but not its mRNA, is frequently lost or reduced in a wide range of human malignancies, such as colon, lung, prostate, breast, brain tumors, germ cell tumors, and non-Hodgkin’s lymphoma." (PMID 27042198, 2016).